SLC22A11 (solute carrier family 22 member 11)
Description:
Antiporter that mediates the transport of conjugated steroids and other specific organic anions at the basal membrane of syncytiotrophoblast and at the apical membrane of proximal tubule epithelial cells, in exchange for anionic compounds. May be responsible for placental absorption of fetal-derived steroid sulfates such as estrone sulfate (E1S) and the steroid hormone precursor dehydroepiandrosterone sulfate (DHEA-S), as well as clearing waste products and xenobiotics from the fetus. Maybe also be involved in placental urate homeostasis. Facilitates the renal reabsorption of organic anions such as urate and derived steroid sulfates. Organic anion glutarate acts as conteranion for E1S renal uptake. Possible transport mode may also include DHEA-S/E1S exchange. Also interacts with inorganic anions such as chloride and hydroxyl ions, therefore possible transport modes may include E1S/Cl(-), E1S/OH(-), urate/Cl(-) and urate/OH(-). Also mediates the transport of prostaglandin E2 (PGE2) and prostaglandin F2-alpha (PGF2-alpha) and may be involved in their renal excretion. Also able to uptake anionic drugs, diuretics, bile salts and ochratoxin A. Mediates the unidirectional efflux of glutamate and aspartate. Glutamate efflux down its transmembrane gradient may drive SLC22A11/OAT4-mediated placental uptake of E1S.
Synonyms: OAT4; hOAT4
Tractability: Small molecule: an approved drug acts on it; it belongs to a druggable protein family. Antibody: UniProt places it where antibodies can reach, with high confidence; its Gene Ontology location is reachable by antibodies, with high confidence; UniProt predicts a signal peptide or a membrane-spanning region. PROTAC: a small molecule that binds it is known.
Target class: SLC superfamily of solute carriers; Electrochemical transporter; SLC22 family of organic cation and anion transporters; Transporter
Gene: Protein-coding gene on chromosome 11 (64,555,690 to 64,572,875, forward strand). Ensembl gene ENSG00000168065.
Subcellular location: Cell membrane; Apical cell membrane; Basal cell membrane
Pathways (Reactome):
Transport of small molecules: Organic anion transport by SLC22 transporters
Gene Ontology:
Molecular function: prostaglandin transmembrane transporter activity; protein binding; secondary active transmembrane transporter activity; solute:inorganic anion antiporter activity; transmembrane transporter activity
Biological process: prostaglandin transport; transmembrane transport; urate metabolic process
Cellular component: apical plasma membrane; basal plasma membrane; external side of plasma membrane; extracellular exosome; plasma membrane; membrane
Genetic constraint (gnomAD): Loss-of-function variants: 42 observed, 49.18 expected, observed/expected ratio (o/e) 0.85, 90% interval 0.67 to 1.11. The upper end of that interval is the gene's LOEUF score, 1.11, which puts it in group 4 of 6, group 1 being the genes least tolerant of losing a copy. Missense variants: 685 observed, 740.43 expected, observed/expected ratio (o/e) 0.93, 90% interval 0.87 to 0.99. Synonymous variants: 304 observed, 320.99 expected, observed/expected ratio (o/e) 0.95, 90% interval 0.86 to 1.04.
Homologues: Orthologues: chimpanzee SLC22A11 (99% identical), dog SLC22A11 (73% identical), pig SLC22A11 (60% identical), zebrafish oatx (38% identical), zebrafish si:dkey-166k12.1 (30% identical), Drosophila melanogaster Orct2 (29% identical), zebrafish slc22a5 (29% identical), zebrafish slc22a21 (28% identical), Drosophila melanogaster Orct (27% identical), Caenorhabditis elegans oct-2 (27% identical), zebrafish slc22a4 (27% identical), Caenorhabditis elegans oct-1 (26% identical), and 44 more. Paralogues in human: SLC22A12 (53% identical), SLC22A10 (47% identical), SLC22A25 (44% identical), SLC22A24 (44% identical), SLC22A9 (42% identical), SLC22A6 (42% identical), SLC22A8 (41% identical), SLC22A7 (33% identical), SLC22A13 (30% identical), SLC22A5 (29% identical), SLC22A2 (28% identical), SLC22A1 (28% identical), and 10 more.
Diseases named in the same sentence as SLC22A11 in open-access papers:
SLC22A11 is named in the same sentence as 16 diseases in open-access papers, as found by Europe PMC text mining. Sharing a sentence is not in itself a finding about the gene and the disease. The quoted sentences say what the papers report.
gout (15 papers, 2012 to 2025). A condition characterized by painful swelling of the joints, which is caused by deposition of urate crystals. "Some studies have reported polymorphisms in SLC22A11 associated with serum urate concentrations and gout." (PMID 38222853, 2024). "Our analysis of the rs17300741 G > A in SLC22A11 suggests a higher genetic risk for HU or gout in Asian and NHPI subgroups compared with EUR." (PMID 34986901, 2022). "The SNP rs17300741 (G > A) in the SLC22A11 was associated with renal urate underexcretion type gout in the Japanese population (p = 0.049)." (PMID 34986901, 2022). "In future clinical and epidemiological studies, it will be important to investigate why loci such as SLC16A9 and SLC22A11 inconsistently associate with gout." (PMID 25889045, 2015). "It is therefore counter-intuitive that the association of SLC22A11 should be restricted to gout cases ascertained by less stringent criteria." (PMID 24360580, 2013). "At block 2 (SLC22A11) rs2078267 has previously been convincingly associated with gout in European Caucasian (OR = 0.88, P = 2.3 × 10-5;) but the NZ European Caucasian sample set is inconsistent with these findings (OR = 0.98, P = 0.82)." (PMID 24360580, 2013). "The aim of this study was to test genetic variation across the SLC22A11/SLC22A12 locus for association with risk of gout in NZ sample sets." (PMID 24360580, 2013). "Finally, a non-additive interaction between diuretic use and genotype at each of SLC2A9 and SLC22A11 in the risk of gout in hypertensive people has been reported in the Atherosclerosis Risk in Communities study." (PMID 25889045, 2015). "GWASs and meta-analyses have identified several genes associated with gout susceptibility, including SLC2A9, SLC22A12, and SLC22A11." (PMID 41137353, 2025). "Among the other genes significantly associated with gout, seven loci have also been previously identified in GWAS, including those in the genes SLC17A1, GCKR, SLC22A11, ADH1B, MLXIPL, RREB1 and SLC16A9." (PMID 41075270, 2025). "This study examines six rare nonsynonymous variants in the SLC22A11, SLC22A13, and SLC17A1 genes found in a cohort of 150 Czech patients of Caucasian origin with primary hyperuricemia and gout." (PMID 38222853, 2024). "In a cohort of 150 Czech patients with primary hyperuricemia and gout, we examined all coding regions and exon–intron boundaries of SLC22A11, SLC22A13, and SLC17A1 using PCR amplification and Sanger sequencing." (PMID 38222853, 2024). "GWAS have revealed that SLC22A11 rs17300741 was associated with SUA levels, while rs2078267, rs2186571, rs17299124 and rs17300741 were associated with gout." (PMID 35922835, 2022). "Recent reports also show the significance of transporter genes such as ABCG2, NPT1/SLC17A1, MCT9/SLC16A9, and OAT4/SLC22A11, for the pathogenesis of gout." (PMID 24366390, 2014). "This SNP, which maps several hundred kilobases upstream of SLC22A11, further implicates this region in the etiology of gout." (PMID 24360580, 2013). "Given the lower allele frequency of this variant in Polynesians (<0.10 in the less admixed samples), a larger sample size is required for more robust conclusions about the possible role of SLC22A11 in gout in Polynesian people." (PMID 24360580, 2013). "While no other identified genes were currently linked to approved gout medications, the associated drugs targeting genes such as ABCG2, SLC22A11, and ADH1B—involved in metabolic and inflammatory pathways—may hold potential for repurposing in gout treatment." (PMID 41075270, 2025). "In addition, many other genes, such as ABCG2, SLC22A11, and SLC17A1, also showed strong associations with gout, all surpassing the genome-wide significance threshold after the Bonferroni correction test (P = 0.05/19203 = 2.60 × 10−6)." (PMID 41075270, 2025).
gout (continued). "Recent GWAS identified genetic variants in urate transporters (ABCG2, SLC2A9, SLC22A11) and metabolic genes (GCKR, ADH1B) to be associated with the transition from hyperuricaemia to gout, and several of these associated with serum urate (SU) and gout in previous studies." (PMID 35633389, 2022). "SLC22A11 in particular is known to be a drug target for probenecid, a SLC22A11 inhibitor, used in the gout prevention and to increase antibiotic blood levels, yet its direct role in lung disease treatment is still unknown." (PMID 29725345, 2018). "In contrast, SLC22A11 is not consistently associated with gout, and the evidence for association reported by Köttgen and colleagues in Europeans (OR = 1.14) has not been replicated elsewhere (OR = 0.98)." (PMID 25889045, 2015). "A haplotype block 1 SNP (rs17299124) (upstream of SLC22A11) was associated with gout in less admixed Polynesian sample sets, but not European Caucasian (odds ratio; OR = 3.38, P = 6.1 × 10-4; OR = 0.91, P = 0.40, respectively) sample sets." (PMID 24360580, 2013). "Studies have shown that HPRT and PRPS1 gene mutations seem to be the main cause of primary gout; SLC22A11 gene mutation is associated with RUE (renal underexcretion) gout; ABCG2 seems to be one of the reasons for the genetic heterogeneity of ROL (renal overload) and RUE gout." (PMID 35922835, 2022). "None of the variants of the known gout and hyperuricemia-related genes were co-segregated with the disease phenotype in this family, including ABCG2, SLC2A9, SLC22A11, SLC22A12, SLC17A1, SLC17A3, PDZK1, and INHBB." (PMID 39433541, 2024). "Within haplotype block 2 (SLC22A11) we could not replicate previous reports of association of rs2078267 with gout in European Caucasian (OR = 0.98, P = 0.82) sample sets, however this SNP was associated with gout in Polynesian (OR = 1.51, P = 0.022) sample sets." (PMID 24360580, 2013).
hyperuricemia (4 papers, 2022 to 2025). An abnormally high level of uric acid. "Associations between SLC2A9, SLC22A12 and SLC22A11 SNPs and hyperuricemia." (PMID 41137353, 2025). "A total of 194 Tibetan patients with hyperuricemia and 304 healthy Tibetan controls were enrolled, and polymorphisms in SLC2A9 (rs1014290), SLC22A12 (rs559946), and SLC22A11 (rs1783811) were identified using high-resolution melting." (PMID 41137353, 2025). "Association between SLC2A9, SLC22A12 and SLC22A11 polymorphisms and the risk of higher SUA values in hyperuricemia group." (PMID 41137353, 2025). "In this case-control study, we investigated for the first time the association between rs1014290 (SLC2A9), rs559946 (SLC22A12), and rs1783811 (SLC22A11) with SUA levels and hyperuricemia in a Tibetan population." (PMID 41137353, 2025).
breast carcinoma (1 paper, 2014). "All analyzed breast cancer cells depicted similar expression levels of PANX1 and ABCC1 whereas a considerable variability of ANKH and SLC22A11 expression was observed." (PMID 25496233, 2014).
coronary heart disease (1 paper, 2016). "An instrumental variable analysis based solely on rs2078267 at the SLC22A11 locus yielded an OR for risk of coronary heart disease of 1·19 (95% CI 0·75–1·78) per 1 SD increment in urate concentration." (PMID 26781229, 2016).
Insulin resistance (1 paper, 2015). Increased resistance towards insulin, that is, diminished effectiveness of insulin in reducing blood glucose levels. "The strength of the associations between the SLC22A11 and LRRC16A loci was not affected by the serum uric acid levels or other confounders, which suggests a greater likelihood of a direct effect on insulin secretion and insulin resistance." (PMID 25617895, 2015).
pancreatic ductal adenocarcinoma (1 paper, 2018). An infiltrating adenocarcinoma that arises from the epithelial cells of the pancreas. "For example, a high level of SLC22A18 has been associated with the smaller tumor size while lower levels of SLC22A1 and SLC22A11 have been associated with angioinvasion in pancreatic ductal adenocarcinoma (PDAC)." (PMID 29703252, 2018).
Stroke (1 paper, 2019). Sudden impairment of blood flow to a part of the brain due to occlusion or rupture of an artery to the brain. "The mRNAs of ID3, MBTPS1, NOG, and SFXN2 have lower concentrations (are down-regulated) in the stroke samples (log FC = − 0.915, − 0.356, − 0.752, − 0.301, respectively) while BMX and SLC22A11 are up-regulated (log FC = 0.456, 0.365) in the stroke patients." (PMID 31391037, 2019). "Indeed, the differences in expression level for SLC22A11 between stroke and control are not even statistically significant." (PMID 31391037, 2019).
Tumor (2 papers, 2018 to 2022). "While multiple comparisons had no DE genes in the entire expressed gene list (i.e., Stage III vs. Stage IV), there were 6 DE SLC22 genes in the Tumor Size and Progression comparison in KIRC [SLC22A2, SLC22A5, SLC22A6, SLC22A11, SLC22A12, SLC22A18] (T3 v T4)." (PMID 36230695, 2022).
infection (1 paper, 2021). The state of being infected such as from the introduction of a foreign agent such as serum, vaccine, antigenic substance or organism. "Concerning pharmacokinetics–related polymorphisms, SLC22A11 rs11231809 polymorphism was associated with the risk of infection." (PMID 33776761, 2021).
SLC22A11 also shares sentences with these, for which no sentence is quoted: bladder cancer (1 paper); diabetes (1); Hypercholesterolemia (1); Hypertension (1); ischaemic heart disease (1); lung disease (1); pancreatic cancer (1).